HOXB9 (homeobox B9)
Diseases named in the same sentence as HOXB9 in open-access papers (continued):
Sharing a sentence is not in itself a finding about the gene and the disease.
gastric cancer (16 papers, 2015 to 2025). A primary or metastatic malignant neoplasm involving the stomach. "Some studies have suggested that HOXB9 is downregulated in gastric cancer and colon cancer and is associated with poor clinical outcomes, which suggests it plays an important role as a tumor suppressor gene." (PMID 37301547, 2023). "In the present study, we demonstrated that the expression of HOXB9 decreased in gastric carcinoma and was associated with malignancy and metastasis." (PMID 26536658, 2015). "While HOXB9 has been implicated in tumorigenesis and metastasis, its mechanisms are variable and its role in gastric carcinoma (GC) remains unclear." (PMID 26536658, 2015). "However, HOXB9 downregulation was also reported to be associated with a poor survival in gastric cancer patients, highlighting conflicting hypotheses regarding the role of HOXB9 in cancer." (PMID 36803556, 2023). "Therefore, the low expression of HOXB9 may be an independent risk factor for poor prognosis of gastric carcinoma." (PMID 34306077, 2021). "However, it has also been reported that downregulation of HOXB9 is associated with poor survival of gastric carcinoma patients, highlighting conflicting hypotheses about HOXB9’s role in cancer." (PMID 33171691, 2020). "On the other hand, the overexpression of HOXB9 also serves as a beneficial prognostic factor in certain cancers, including gastric cancers." (PMID 38928496, 2024). "The correlation between HOXB9 expression, prognosis, as well as clinical and pathological factors in patients with gastric cancer was assessed, and the contribution of HOXB9 expression to tumor cell lymphangiogenesis in vitro was analyzed." (PMID 35330327, 2022). "On the contrary, decreased HOXB9 was considered as a factor for poor prognosis in colon adenocarcinoma and pancreatic cancer, as well as gastric cancer." (PMID 36158877, 2022). "The expression of HOXB9 in normal tissues adjacent to a gastric carcinoma, in intestinal-type gastric adenocarcinoma and in diffuse-type gastric adenocarcinoma was examined by immunohistochemistry." (PMID 26536658, 2015). "Taken together, these findings suggest that gastric carcinomas have downregulated HOXB9 expression, which was correlated with GC malignancy and metastasis." (PMID 26536658, 2015). "The mRNA level expression of HOXB9 gene in 10 gastric carcinomas and its adjacent normal tissues were examined using real-time quantitative PCR." (PMID 26536658, 2015). "In summary, reduced HOXB9 expression was found to correlate with malignancy and metastasis of gastric carcinoma." (PMID 26536658, 2015). "Positive staining was found in normal tissues adjacent to gastric carcinoma, with HOXB9 mainly enriched in the nuclei of epithelial cells in gastric glands adjacent to the basement membrane." (PMID 26536658, 2015). "On the contrary, HOXB9 was also reported to be served as a tumor suppressor gene in some cancer types, and elevated HOXB9 levels were found to predict good overall survival in colon cancer and gastric cancer." (PMID 36158877, 2022). "In addition, the expression of HOXB9 positively correlated with the progression of gastric cancer and the expression of a lymphangiogenesis marker." (PMID 35330327, 2022). "For example, HOXB9 promotes differentiation and mesenchymal-epithelial transition, while inhibiting migration and invasion, in both colon adenocarcinoma and gastric carcinoma cells." (PMID 33051260, 2020). "However, increased expression of HOXB9 showed better overall survival in colon adenocarcinoma, pancreatic ductal adenocarcinoma and gastric carcinoma patients, indicating HOXB9 played an opposite role in these cancer progression." (PMID 29724991, 2018). "In this paper, we demonstrated that the expression of HOXB9 was downregulated in gastric carcinomas and its re-expression suppressed the proliferation, migration, and invasion of gastric carcinoma cells through the induction of mesenchymal-to-epithelial transition (MET)." (PMID 26536658, 2015).
gastric cancer (continued). "Therefore, the results of the present study suggested that HOXB9 is a tumor suppressor in gastric carcinoma, and its activity was controlled by different regulatory mechanisms such as the hexapeptide motif as a “brake” in this case." (PMID 26536658, 2015). "In gastric carcinomas, HOXB9 downregulation is correlated with poor survival, suggesting that HOXB9 may be a tumor suppressor instead of an oncogene in gastric carcinomas." (PMID 26536658, 2015). "However, HOXB9 could also delay tumor progression in other kinds of tumors such as gastric cancer and pancreatic cancer." (PMID 36387262, 2022). "However, some studies proposed a thoroughly opposite view, concluding that the downregulation of HOXB9 was correlated with the poor survival prognosis of patients bearing adenocarcinoma of the colon, ductal adenocarcinoma of the pancreas, and gastric carcinoma." (PMID 34055607, 2021). "However, decreased HOXB9 expression has been reported related to poor survival in gastric cancer." (PMID 28808656, 2017). "In contrast, HOXB9 was reported to induce tumor cell differentiation via mesenchymal-to-epithelial transition (MET) and was correlated with favorable prognosis in gastric carcinoma." (PMID 33411683, 2020).
hepatocellular carcinoma (13 papers, 2015 to 2023). A malignant tumor that arises from hepatocytes. "Increased HOXB9 expression was significantly associated with poor disease-free survival (p < 0.001) and the prognosis for overall survival (p < 0.001), as previously reported for hepatocellular carcinoma." (PMID 35634239, 2022). "Protein encoded by HOXB9 functioned as oncoprotein and could accelerate cell proliferation and invasion in endometrial cancer, colorectal cancer, and hepatocellular carcinoma cells." (PMID 36387262, 2022). "HSPA5 (GRP78) activates the Wnt/HOXB9 pathway to promote invasion and metastasis of hepatocellular carcinoma by chaperoning LRP6." (PMID 34918006, 2022). "GRP78 promotes malignant phenotype of hepatocellular carcinoma by activating the Wnt/HOXB9 signaling pathway and chaperoning LRP6." (PMID 35535309, 2022). "Homeobox B9 (HOXB9), a homeodomain-containing transcription factor, may play a role in hepatocellular carcinoma (HCC) progression." (PMID 36158877, 2022). "Notably, cDNA microarray analysis showed that loss of FAT10 inhibits HOXB9 expression in liver carcinoma cells, suggesting FAT10 affects HCC tumor metastasis by regulating HOXB9." (PMID 36386217, 2022). "HOXB9 functions as a transcriptional activator and induces TGFβ1 in hepatocellular carcinoma (HCC) cells, enhancing their migratory and invasive potential." (PMID 34617205, 2022). "HOXB9 expression is elevated in a range of cancers including breast, NSCLC and hepatocellular carcinoma, but decreased expression has been related to poor prognosis in others." (PMID 25860510, 2015). "For example, FAT10 upregulated HOXB9 in hepatocellular carcinoma (HCC), through the β-catenin/TCF4 signaling pathway and facilitates HCC invasion in vitro." (PMID 36674743, 2023).
lung carcinoma (12 papers, 2015 to 2026). "In relation to lung cancer, previous studies have shown that the upregulation of HOXB9 (Homeobox protein Hox-B9) is associated with lower patient survival and is a predictor of poorer clinical outcomes." (PMID 28587176, 2017). "For example, HOXB9, a class 1 homeobox gene associated with tumorigenesis, metastasis, and poor prognosis, is upregulated by Wnt signaling and promotes lung cancer metastasis." (PMID 26544896, 2015). "The association of HOXB9 and cancer progression was also found in breast and lung cancers." (PMID 36674764, 2023). "Thus, an appealing hypothesis is that HOXB9 expression may be caused by increased Wnt activity due to high GalNAc-T14 expression in lung cancer, and is responsible for the increased metastatic potential." (PMID 26544896, 2015). "Elevated HOXB9 was correlated with the advanced clinicopathological staging and identified as a prognostic marker in lung cancer." (PMID 36158877, 2022). "A study has shown that signaling through the WNT/TCF pathway in lung cancer promotes metastatic dissemination to brain and bone by downstream activation of HOXB9 and LEF1 genes." (PMID 33411683, 2020). "Accordingly, short hairpin RNA (shRNA)-mediated knockdown of HOXB9 in lung cancer cells reduces their invasive phenotype." (PMID 33171691, 2020). "Meanwhile, another study showed that PCAF-mediated acetylation of HOXB9 inhibited lung cancer progression." (PMID 33411683, 2020). "The acetylated form of HOXB9 decreases the ability of lung cancer cells to migrate and to promote tumor growth in mice." (PMID 33171691, 2020). "The acetylation at K27 of HOXB9 inhibits the function of HOXB9 in promoting lung cancer cell migration and tumor growth." (PMID 28587176, 2017). "Herein, we demonstrated that GalNAc-T14, the expression of which has been previously correlated with lung cancer recurrence, promoted metastatic potential through Wnt/β-catenin-dependent HOXB9 expression." (PMID 26544896, 2015). "Considering the positive correlation between GalNAc-T14 and HOXB9 in a cell model, the potential positive correlation between GalNAc-T14 and HOXB9 expression was examined in other lung cancer cell models and in cancer tissue." (PMID 26544896, 2015). "In patients with lung cancer, cold atmospheric plasma (CAP) enhances the interaction between HOXB9 and the acetyltransferase P300/CBP-associated factor (PCAF), thereby increasing the level of K27 acetylation on HOXB9." (PMID 41513612, 2026). "It has been found that HOXB9 could enhance the ability of lung cancer cells by regulating the proliferation and invasion through regulating epithelial-to-mesenchymal transition." (PMID 36158877, 2022). "Previous studies have shown that HOXB9 overexpression may promote distal metastasis, and is correlated with clinical outcomes in breast, colon, and lung cancers, which links HOXB9’s biological function to solid tumour invasion and metastasis." (PMID 34247196, 2021). "Considering the critical role of HOXB9 in lung cancer progression and metastasis, we examined its expression in clinical NSCLC samples and cell lines and conducted knockdown and overexpression experiments to evaluate its impact on BBB breakdown and brain metastasis formation." (PMID 33411683, 2020). "This illustrates that HOXB9 enhances the ability of lung cancer to develop brain metastases." (PMID 33411683, 2020). "Thus, targeting β-catenin with a small molecule in GalNAc-T14- and HOXB9-expressing lung cancers may be an effective therapy to suppress metastatic properties." (PMID 26544896, 2015). "Interestingly, in two independent clinicogenomics studies (GSE31210 and GSE8894), HOXB9 expression was most significantly altered in patients with high-grade tumors (GSE31210) and in recurrent lung cancer (GSE8894), respectively." (PMID 26544896, 2015).
colon cancer (11 papers, 2014 to 2024). "HOXB9 (homeobox protein Hox-B9) induces angiogenesis in a tumor, and it is associated with poor prognosis in patients with BC or colon cancers." (PMID 35330327, 2022). "Intriguingly, elevated HOXB9 expression has been linked to both favorable and poor prognosis in colon cancer patients." (PMID 33411683, 2020). "It should be noted that there is some controversy surrounding the role and expression of HOXB9 in gastric and colon cancer." (PMID 37301547, 2023). "Colon cancer patients having low levels of the acetylated HOXB9 form have a more favorable outcome compared to patients with high levels of the non-acetylated HOXB9 form." (PMID 33171691, 2020). "Next, BALB/c nude mice transplanted with xenografts that had been previously established using HOXB9-overexpressing colon cancer cells were treated intraperitoneally with bevacizumab (5 mg/kg, weekly)." (PMID 24885802, 2014). "Preliminary investigations (data not shown) revealed that candidate markers differentially expressed between PC- and Lgr5+-initiated mouse tumors such as DCLK1 and HOXB9 were not equally discriminative among patient-derived colon cancers." (PMID 38902475, 2024).
pancreatic cancer (11 papers, 2022 to 2025). "Thus, the regulation of TGFβ signaling in HOXB9 may be an important pharmacological pathway underlying the invasion and metastasis of pancreatic cancer cells." (PMID 35634239, 2022). "HOXB9 inhibits the proliferation of pancreatic cancer cells by blocking cell cycle progression through the DNMT1/RBL2/c-Myc axis." (PMID 37301547, 2023). "The DNMT1/RBL2/c-Myc axis is involved in the inhibitory effect of HOXB9 on pancreatic cancer cell proliferation by blocking cell cycle progression." (PMID 37301547, 2023). "Our data suggested that TGFβ signaling induced by HOXB9 expression resulted in chemoresistance in pancreatic cancer cells through EMT." (PMID 35634239, 2022). "First, a large amount of experimental data confirmed that HOXB9 overexpression could promote MT in various tumours (such as breast, lung and pancreatic cancers)." (PMID 40936205, 2025). "Subsequently, FERMT2 promotes pancreatic cancer progression by downregulating HOXB9 and E-cadherin." (PMID 38910148, 2024). "RBL2 and c-myc were essential for HOXB9 to inhibit pancreatic cancer cell proliferation." (PMID 39337523, 2024). "The results showed that HOXB9 could strongly up-regulate the TGFβ cascade in the human pancreatic cancer cell lines, and the TGFβ recombinant induction contributed significantly to the reversal of trends observed in the siHOXB9 experiments." (PMID 35634239, 2022). "Our results suggested that HOXB9 may serve as a novel biomarker for selecting patients with pancreatic cancer who are more likely to benefit from chemotherapy and surgery." (PMID 35634239, 2022). "In the present study, we demonstrated that HOXB9 could promote the expression of angiogenic factors and EMT in pancreatic cancer through the TGFβ pathway." (PMID 35634239, 2022). "In conclusion, HOXB9 expression could mediate angiogenesis, EMT, and cancer stemness through the TGFβ pathway, thereby resulting in chemoresistance and poor overall outcomes in patients with pancreatic cancer." (PMID 35634239, 2022).
endometrial cancer (10 papers, 2018 to 2025). Primary or metastatic malignant neoplasm involving the endometrium (mucous membrane that lines the endometrial cavity). "Here, we demonstrated that the expression of HOXB9 was increased in endometrial cancer, and associated with histological grade and lymph node metastasis." (PMID 29724991, 2018). "Also, poor prognosis of patients with endometrial cancer is associated with higher levels of HOXA4, HOX5, HOXA6, HOXA7, and HOXB9 expression, whereas favorable prognosis of patients with endometrial cancer is associated with higher levels of HOXB5 and HOXB6 expression." (PMID 30866492, 2019). "This study links fatty acids to polyamine buildup, reveals a mechanism for metabolic syndrome-driven endometrial cancer, and points to HOXB9 and ODC1 as potential therapeutic targets." (PMID 41402312, 2025). "The authors found that the expression level of HOXB9 in normal proliferative endometrium, atypical endometrial hyperplasia, and endometrial carcinoma gradually increased (p = 0.0196)." (PMID 39518001, 2024). "In endometrial carcinoma, the expression of HOXB9 correlated only with the histological grade (p = 0.0081) and the status of metastasis in lymph nodes (p = 0.001)." (PMID 39518001, 2024). "In the Endometrial Carcinoma dataset (CPTAC, Cell 2020), HOXB9 was altered in 2.47% of 81 cases, whereas in the Uterine Corpus Endometrial Carcinoma dataset (TCGA, Firehose Legacy), HOXB9 was altered in 2.2% of 545 cases." (PMID 36803556, 2023). "In the dataset of Uterine Corpus Endometrial Carcinoma (TCGA, PanCancer Atlas), HOXB9 was altered in 2.84% of 529 cases." (PMID 36803556, 2023). "We found that the high expression ratio and expression level of HOXB9 in normal proliferative endometrium, atypical endometrial hyperplasia and endometrial carcinoma were gradually increased (P = 0.0196)." (PMID 29724991, 2018). "To determine the expression of HOXB9 in EC, we analyzed its expression in a series of 88 endometrial carcinoma, 15 normal proliferative endometrium and 21 atypical endometrial hyperplasia by immunohistochemistry." (PMID 29724991, 2018). "In this study, we found the expression of HOXB9 in endometrial carcinoma is higher than normal proliferative endometrium and atypical endometrial hyperplasia." (PMID 29724991, 2018). "In endometrial carcinoma, HOXB9 expression correlated only with histological grade (P = 0.0081) and lymph node metastasis status (P = 0.001)." (PMID 29724991, 2018). "An analysis was also performed for homeobox B9 (HOXB9), and an increase in its expression in endometrial cancer samples compared to normal endometrium was observed, suggesting that HOXB9 may be a prognostic marker for EC." (PMID 35163161, 2022). "Recent studies have also shown the overexpression of HOXB9 in endometrial cancer, which could potentially be a prognostic marker and a therapeutic target." (PMID 35163161, 2022). "Taken together, for the first, we demonstrated the function and mechanism of HOXB9 in regulating endometrial cancer progression, and indicated HOXB9 may be a novel prognostic marker of endometrial cancer." (PMID 29724991, 2018). "In addition, elevated HOXB9 predicts a poor prognosis in endometrial cancer patients." (PMID 29724991, 2018). "However, the function of HOXB9 and its precise mechanism in regulating endometrial cancer progression remains unknown." (PMID 29724991, 2018). "E2F3 is a direct downstream target of HOXB9 and is overexpressed in endometrial carcinoma tissues, and E2F3 overexpression enhances endometrial carcinoma cell migration ability." (PMID 34657558, 2021). "In endometrial cancer, the knocking down E2F3 could inhibit the ability of HOXB9 in promoting migration of tumor cell." (PMID 40070576, 2025). "Meanwhile, we analyzed the correlation of HOXB9 and E2F3 expression in 88 endometrial carcinoma." (PMID 29724991, 2018).
endometrial cancer (continued). "However, the potential relationship between HOXB9 and endometrial cancer (EC) has not yet been comprehensively analyzed and fully understood." (PMID 36803556, 2023).